CTCFL (CCCTC-binding factor like)
Diseases named in the same sentence as CTCFL in open-access papers (continued):
Sharing a sentence is not in itself a finding about the gene and the disease.
male infertility (2 papers, 2016 to 2021). The inability of the male to effect fertilization of an ovum after a specified period of unprotected intercourse. "In addition, at least two putative genes related to male infertility, CTCFL and SPO11, are located in the middle of the region detected on BTA13 (13:58456868–59951247)." (PMID 27842509, 2016).
anaplastic astrocytoma (1 paper, 2013). "Immunoreaction to CTCFL was negative in all anaplastic astrocytomas (0/15), diffuse astrocytomas (0/48), pilocytic astrocytomas (0/38) and normal brain samples (0/40) examined." (PMID 23592437, 2013).
astrocytomas (1 paper, 2013). "Also noteworthy, immunohistochemical staining revealed that CTCFL expression was frequently detected in GBM specimens but was completely negative in all less aggressive astrocytomas (Grade I, II or III) cases." (PMID 23592437, 2013).
cutaneous melanoma (1 paper, 2018). A primary melanoma arising from atypical melanocytes in the skin. "In the cutaneous melanoma PanCancer Atlas study (provisional), 11 of 27 samples (40.7%) with CTCFL mutations had lesions in one of the four MSI associated genes or the POLE or POLD1 genes." (PMID 30275357, 2018).
head and neck cancer (1 paper, 2020). A primary or metastatic malignant neoplasm affecting the head and neck. "Moreover, there is a clear correlation between amplification of CTCFL and its increased expression in several cancer types including ovarian, uterine, cervical, lung squamous, and head and neck cancer." (PMID 32393311, 2020).
ICF syndrome (1 paper, 2008). "Aberrant hypomethylation has been hypothesized to contribute to cancer progression by activating oncogenes such as H-RAS, BORIS/CTCFL, FGFR1, c-MYC, or by retrotransposon activation or by increasing chromosome instability as in ICF syndrome." (PMID 19506729, 2008).
Insulin resistance (1 paper, 2018). Increased resistance towards insulin, that is, diminished effectiveness of insulin in reducing blood glucose levels. "We detected transcription factors CTCF, CTCFL, and Egr1 binding to the genomic region overlapping the differentially methylated CpG within EML3 gene; out of these, CTCF is proved to mediate glucagon production and Egr1 is responsible for insulin resistance." (PMID 30545422, 2018).
renal calculi (1 paper, 2024). "By analyzing the differential expression in pediatric renal calculi, we identified four differentially expressed genes: CTCFL, MYH11, MyoD1, and PAX5." (PMID 39242558, 2024).
Testicular atrophy (1 paper, 2012). Wasting (atrophy) of the testicle (the male gonad) manifested by a decrease in size and potentially by a loss of fertility. "We find that absence of CTCFL in mice causes sub-fertility because of a partially penetrant testicular atrophy." (PMID 22709888, 2012).
type 2 diabetes (1 paper, 2017). "Prudent-associated intergenic SNP rs13042507 is located near the CTCFL gene previously associated with type 2 diabetes (T2D)." (PMID 28644415, 2017).
cancer (80 papers, 2005 to 2025). A tumor composed of atypical neoplastic, often pleomorphic cells that invade other tissues. "This indicates that the genes deregulated by CTCFL are not only involved in relevant cancer-associated processes (such as signaling pathways and extracellular component organization ), but they are also differentially expressed in OC patients." (PMID 35132075, 2022). "One interesting member of the cancer testis gene family is BORIS/CTCFL, which encodes a homologue of the insulator protein CCCTC binding factor (CTCF)." (PMID 29649096, 2018). "The most common mechanism causing re-expression of CTCFL in cancer is promoter hypomethylation." (PMID 30275357, 2018). "To further test, if ERV total, L1‐5′UTR and L1‐ORF2 expression correlated with genomic de‐repression, we analyzed the CTCFL gene, which is known to represent a hypomethylated DNA state in cancers, including HGSOC." (PMID 40492347, 2025). "We mainly focus on the role of CTCFL in testicular and cancer development, highlighting its interaction with CTCF at CTCF binding sites to regulate target genes." (PMID 39430552, 2024). "This review aims to provide a comprehensive analysis of the distinct amino acid sequences, the target sites, expressions patterns and functions of CTCF and CTCFL in normal tissues and cancers." (PMID 39430552, 2024). "Despite their distinct expression patterns, the cooperative and competitive mechanisms by which CTCF and CTCFL regulate target gene expression in spermatocytes and cancer cells remain inadequately understood." (PMID 39430552, 2024). "In this review, we comprehensively examine the literature on the divergent amino acid sequences, target sites, expression profiles and functions of CTCF and CTCFL in normal tissues and cancers." (PMID 39430552, 2024). "Conversely, CTCFL expression is predominantly restricted to the adult male testis but is aberrantly expressed in certain cancers." (PMID 39430552, 2024). "It has been demonstrated that the transcriptional regulator CTCFL modifies the expression of several CT genes, which are frequently aberrantly activated in cancer cells but silent in normal tissues." (PMID 39598359, 2024). "In cancers, CTCFL overexpression competes with CTCF for DNA binding, leading to aberrant gene expression, a more relaxed chromatin state, and altered chromatin loops." (PMID 39430552, 2024). "This review represents the first effort to systematically summarize how differential expression patterns of CTCF and CTCFL influence gene regulation and chromatin architecture across normal somatic cells, sperm and cancer cells." (PMID 39430552, 2024). "Upregulation of CTCFL is required for resistance to ALK inhibition in cancer cells via promoting chromatin interactions." (PMID 37120564, 2023). "Together, this suggests that the selected genes are not only CTCFL-driven genes involved in cancer pathways and deregulated in OC patients; but they are also significantly associated with the survival of these patients." (PMID 35132075, 2022). "OC shows the highest expression of CTCFL among cancer types; however, the downstream genes and pathways deregulated by it are not fully described in OC." (PMID 35132075, 2022). "Controlling the false discovery rate at 5%, ECAR selected six genes CHRM3, CTCFL, KCNE2, MLANA, MSMP, TTLL2, many of which have been reported to be associated with lung function or cancer." (PMID 34857823, 2021). "In HCC, for instance, CTCFL upregulates OCT4 by histone methylation to potentiate cancer stem cell-like properties." (PMID 34721660, 2021). "Investigating the impact of CTCFL overexpression in cancer cells is difficult because of the confounding effects of other genetic and epigenetic alterations." (PMID 32393311, 2020). "CTCFL, however, is frequently aberrantly expressed in numerous cancers due to genetic abnormalities." (PMID 32393311, 2020).
cancer (continued). "What role does CTCFL play in regulating chromatin organization and gene expression in a cancer setting where it is expressed in the presence of CTCF?" (PMID 32393311, 2020). "Despite the finding that CTCFL is aberrantly expressed in numerous cancers, little is known about its impact on chromatin organization and gene regulation and the mechanism underlying its effector functions and interplay with CTCF." (PMID 32393311, 2020). "This study clarifies the unique and combined contribution of CTCF and CTCFL to chromosome organization and transcription, with direct implications for understanding how their co-expression deregulates transcription in cancer." (PMID 32393311, 2020). "As of July 2019, 382 of the 10,950 (3%) cancer samples profiled in cBioPortal were found to have genetic changes in CTCFL, with amplification occurring most frequently (58%) in these patient samples." (PMID 32393311, 2020). "This study clarifies the relative and combined contribution of CTCF and CTCFL to chromosome organization and transcription, with direct implications for understanding how their co-expression deregulates transcription in cancer." (PMID 32393311, 2020). "As a result of this work, we demonstrated that BORIS/CTCFL is controlling a sizeable genetic network in cancer cells." (PMID 29088719, 2017). "BORIS/CTCFL (Brother Of the Regulator of Imprinted Sites / CCCTC-binding Factor Like) is a CT gene that is commonly activated in cancers." (PMID 29088719, 2017). "Taking into account the important role of CTCF in regulating TE expression and epigenetic maintenance, it is possible that the aberrant activation of its germline paralog CTCFL/BORIS in cancer has an impact on repeat physiology and genome stability." (PMID 27588042, 2016). "Recent evidences have highlighted the correlation of BORIS/CTCFL expression with poor overall survival of different cancer patients." (PMID 26185996, 2015). "Aberrant CTCFL/BORIS expression is induced through promoter hypomethylation in early steps of cancer progression, with increased mRNA expression from premalignant to primary tumors and further to metastatic lesions." (PMID 24658009, 2014). "The reference to CTCFL/BORIS brings about an important connection of some meiotic proteins to cancers." (PMID 25408876, 2013). "In fact, CTCFL belongs to the group of cancer testis antigens (CTAs), genes that are normally expressed in testis yet aberrantly expressed in a variety of cancers." (PMID 22709888, 2012). "Aberrant CTCFL expression in cancer could thus rewire enhancer-driven gene programs by altering genome architecture while maintaining CTCF-dependent housekeeping gene expression, thereby supporting continued proliferation." (PMID 41254162, 2025). "Additionally, CTCFL has the capacity to compete with CTCF for a subset of binding sites in cancer cells, thereby influencing chromosome architecture and gene regulation." (PMID 39126025, 2024). "Recent studies have shown that CTCF and CTCFL are co-expressed at all stages of spermatogenesis and in certain cancer cells, suggesting their involvement in both the physiological process of male gametogenesis and tumorigenesis to modulate chromatin architecture." (PMID 39430552, 2024). "Although CTCFL is not expressed in normal tissues except testis and embryonic stem cells, increased expression of CTCFL could be observed in various carcinomas and was correlated with malignant behaviors and drug resistance." (PMID 37120564, 2023). "Furthermore, these genes, together with CTCFL, are good mechanistic predictors of survival and can also be targeted by drugs currently being used or tested in other cancer types." (PMID 35132075, 2022). "Mechanisms causing CIMP are heterogeneous, including mutations in IDH1/2 and SETD2 that were previously reported in specific cancer types, as well as reported for the first time here in new cancer types; the novel overexpression of BORIS/CTCFL spanned several cancer types." (PMID 35134107, 2022).
cancer (continued). "Indeed, CTCFL has largely been studied in a cancer setting which has many other confounding genetic aberrations." (PMID 32393311, 2020). "However, CTCFL is aberrantly activated in a wide variety of cancer types and publicly available data from genomic studies demonstrates that, in the context of cancer, CTCFL exhibits a variety of genetic alterations." (PMID 32393311, 2020). "To mention only a few, we have observed different expression of the CTCFL gene—oncogene—which is tested as a target gene in the immunotherapy of cancer, PADI2—a novel angiogenesis-regulating gene, or USP53—which is a novel molecular biomarker for weight control." (PMID 31756991, 2019). "Thus, CTCFL belongs to the category of so called cancer testis antigens, alternatively termed cancer-germline antigens." (PMID 30275357, 2018). "Abnormal re-expression of CTCFL in these cancer cases could have functional implications by interfering with binding of CTCF in a subset of its sites or by binding to methylated sites where CTCF may be less apt or cannot bind." (PMID 30275357, 2018). "Whether there is a correlation of CTCFL promoter hypomethylation with protein expression in vivo in cancer patients remains untested." (PMID 30275357, 2018). "Moreover, CTCFL protein is rarely expressed in cancers, in contrast to CTCF that is ubiquitously expressed." (PMID 30275357, 2018). "Furthermore, expression of CTCFL is restricted to testis, several types of cancers and a number of cell lines." (PMID 22709888, 2012). "It will be interesting to determine how CTCFL influences rRNA transcription in vivo, as in normal tissues this protein is expressed in a very restricted manner, whereas its expression is upregulated in various types of cancers." (PMID 21059229, 2010). "However, the mechanisms by which CTCF and CTCFL interact to regulate the gene transcription in the testis and cancer, and whether they alter 3D chromatin architecture, remain poorly understood." (PMID 39430552, 2024). "Some cancers present more commonly with CTCFL mutations rather than amplifications, and these could be of significance if the defective protein is expressed." (PMID 30275357, 2018). "In addition to epigenetic promoter hypomethylation that could promote CTCFL re-expression in cancer, genetic lesions may contribute to CTCFL de-repression." (PMID 30275357, 2018). "In this regard, BORIS (CTCFL), a CTCF paralog, is a promising cancer biomarker that is overexpressed and controls transcription in several cancer types, mainly in OC." (PMID 31406110, 2019). "CTCF paralogue, CTCFL (CCCTC-binding factor-Like, also known as BORIS, Brother of the Regulator of Imprinted Sites or CT27: Cancer/Testis antigen 27) is transcribed from a gene in human chromosome 20q13.31 (Gene ID: 140690, Ensembl gene: ENSG00000124092)." (PMID 30275357, 2018). "In this study, we isolated cervical CSCs/CICs by sphere culture, and we identified a cancer testis (CT) antigen, CTCFL/BORIS, that is expressed in cervical CSCs/CICs." (PMID 26849232, 2016). "The germline-specific transcription factor BORIS/CTCFL, a paralog of chromatin architecture protein CTCF, is often erroneously activated in cancers and rewires the epigenome for the germline-like transcription program." (PMID 27588042, 2016). "In cancer, CTCF is thought to be a tumor suppressor, while CTCFL/BORIS has been suggested as an oncogene." (PMID 24658009, 2014). "Therefore, it was identified that CTCFL is one of the most promising CTA by the NCI, and is a known activator of expression of other various cancer testis antigens." (PMID 37235839, 2023). "However, an obstacle to this is that some “phenotype switching” inducers like MITF and BRN2 express poorly in other cancers, and others such as BORIS/CTCFL and PHF19 have been scarcely studied in epithelial cancers." (PMID 36127680, 2022).
cancer (continued). "Similar to other carcinoma, in EC various tumor suppressor gene promotors (MLH1, PTEN, p16, APC, MGMT, RASSF1, PR and CDH1) are hypermethylated, whereas oncogene promotors (BMP, CTCFL, PARP1, CASP8) are hypo- or demethylated." (PMID 35284957, 2022). "Addition to CTCF and cohesin, Brother of The Regulator of Imprinted Sites (BORIS, also known as CTCFL) is an emerging architectural protein, which is a paralog of CTCF and typically expressed in testis and ESCs but aberrantly overexpressed in several cancers." (PMID 33453053, 2021). "CTCFL (or CCCTC-binding factor or BORIS (brother of the regulator of imprinted sites)) regulates testis-specific expression in spermatogenesis and is known to be a cancer antigen." (PMID 33113971, 2020). "The Human Protein Atlas records an absence of CTCFL expression in all cancers examined, including cancers with comparatively high rate of CTCFL amplification such as gastroesophageal, breast, and colon." (PMID 30275357, 2018). "CTCFL promoter hypomethylation was evident in some types of cancers compared with corresponding normal tissues but not in other cancers." (PMID 30275357, 2018). "In most occasions this is not the case and re-expression of CTCFL remains a rare occurrence in cancers." (PMID 30275357, 2018). "The BORIS/CTCFL gene, is a testis-specific CTCF paralog frequently erroneously activated in cancer, although its exact role in cancer remains unclear." (PMID 29088719, 2017). "Brother of the regulator of imprinting sites (BORIS) also designed as CTCFL, CCCTC-binding factor-like, is a DNA-binding protein with functions in cancer not fully understood." (PMID 25279549, 2014). "CTCFL or BORIS (Brother of the Regulator of Imprinted Sites), a paralog of CTCF, has been classified as a cancer-testis antigen as its distribution is reported to be limited to the testis and certain cancers." (PMID 21811597, 2011). "Furthermore, CTCFL was identified as one of the most promising cancer testis antigens by the NCI, and it is known to be important in activating the expression of numerous other cancer testis antigens." (PMID 32393311, 2020). "CTCF paralogue CTCFL is normally not expressed in adult tissues, besides specific stages of spermatogenesis, due to promoter methylation of its gene, but is re-expressed in some cancer cases." (PMID 30275357, 2018). "Indeed, germline-specific CTCFL/BORIS is aberrantly activated in many tumors and cancer cell lines, and its presence there was largely overlooked by the literature devoted to CTCF-cohesin colocalization in cancer cells of somatic origin." (PMID 25408876, 2013). "Interestingly, we found the motif enrichment of BORIS/CTCFL at the class I hotspots (hypo-fragmented in cancer) but not at the class II hotspots (hyper-fragmented in cancer), which suggested the potential associations with the changes in three-dimensional chromatin organizations." (PMID 36482487, 2022).